MITF (melanocyte inducing transcription factor)
Diseases named in the same sentence as MITF in open-access papers (continued):
Sharing a sentence is not in itself a finding about the gene and the disease.
melanoma (continued). "Despite this hypothesis, SMARCA2 was shown to interact with MITF and to partially compensate for SMARCA4 loss in the regulation of MITF-target genes in melanoma cells." (PMID 35323214, 2022). "Moreover, in histological cross-sections melanoma nests were detectable by HE-staining and by immunohistochemical staining of the melanoma-associated markers MiTF, Melan-A, S100 and HMB-45." (PMID 36175453, 2022). "The loss of SCARB1 has been demonstrated to downregulate TF MITF related to the melanocytic state in human melanoma, suggesting that ligand–receptor interaction may affect the cell state of signal receivers." (PMID 35903095, 2022). "We also evaluated the expression of IkB, the inhibitor of NF-κB, and the expression of the microphthalmia-associated transcription factor (MITF), one of the most important melanoma transcriptional regulators, which drives a switch toward a proliferating phenotype." (PMID 36499700, 2022). "However, steadily declining MITF activity levels are linked to proliferation, dedifferentiation/invasion (as seen in melanoma cells), senescence and ultimately cell death." (PMID 36429010, 2022). "Melanomas bearing BRAFV600 E mutations commonly also have altered MITF expression and activity." (PMID 35495634, 2022). "Moreover, ALK and MITF germline alterations were associated with neuroblastoma and melanoma risk, respectively, but this finding is intriguing for possible links with other cancers such as OC." (PMID 36555431, 2022). "Several genes implicated in melanoma FA metabolism have been reported to correlate with the expression of MITF, a hallmark marker of the “proliferative to invasive” phenotype switch, or of AXL, another hallmark marker of a de-differentiated and drug-resistant phenotype." (PMID 35912092, 2022). "Importantly, endogenous BRAF/MITF complexes were also evidenced in BRAF-mutated human melanoma cells, thus emphasizing the conservation of RAF/MITF interaction in human." (PMID 35091687, 2022). "Interestingly, this interaction is conserved among the RAF protein kinase family since BRAF/MITF and CRAF/MITF complexes were also observed in the cytosol of NRAS-mutated mouse melanoma cells." (PMID 35091687, 2022). "MITF is a key transcription factor that regulates melanocyte development, pigmentation and melanoma progression and has been implicated in cellular processes such as differentiation, survival, cell cycle regulation, senescence bypass, autophagy and lysosomal production and regulation." (PMID 36119516, 2022). "Additionally, Microphthalmia-associated transcription factor (MITF) is also expressed in 10%–20% of human melanomas, which induce pigmentation thereby product melanin." (PMID 36620597, 2022). "The expression level of MITF may be associated with melanoma cell behaviour in conjunction with other factors." (PMID 35740696, 2022). "Our analysis of published transcriptomic signatures of melanoma cells and tumors validated that upon MITF loss the expression of differentiation and proliferation genes was diminished and the expression of drug resistant and neural crest-like program was enriched." (PMID 33438577, 2021). "Microphthalmia-associated transcription factor (MITF) is a key regulator that is required for melanocyte differentiation, which may affect malignancy in some melanomas." (PMID 34203771, 2021). "To understand whether the ECM and focal adhesion genes affected upon MITF loss overlap with the gene signature of melanoma cells that have been treated with BRAF inhibitors, we used single-cell RNA-sequencing data of human melanoma xenografts." (PMID 33438577, 2021). "MITF genetically predisposes patients to co-occurring melanoma and RCC." (PMID 34208068, 2021).
melanoma (continued). "In addition, canonical WNT signaling can cooperate with MAPK signaling to regulate MITF expression and activity, which is associated with melanoma cell proliferation." (PMID 34571969, 2021). "The critical role of MITF and the complexity of its regulatory effects become evident in melanoma, where high MITF expression is associated with a differentiated and proliferative phenotype, whereas low MITF expression with dedifferentiation and invasion, but also with cell senescence." (PMID 34573422, 2021). "Furthermore, in a cohort of pre-PD-1 treated melanoma biopsies we found an association between the ‘MITF-low’ microRNAs, miR-100-5p and miR-125b-5p, with clinical benefit from PD-1 checkpoint blockade." (PMID 34771465, 2021). "MITF (microphthalmia-associated transcription factor) plays an integral role in tumour cell differentiation, invasion and survival and has been characterised as an oncogene in 10–20% of patients with melanoma." (PMID 34066022, 2021). "In addition, the present study shows for the first time that PA inhibits melanogenesis via PKA/CREB-associated MITF downregulation in α-MSH-induced melanoma cells." (PMID 33917915, 2021). "In this study, we examined the effects of morin on the melanin contents and tyrosinase activity, as well as the protein expression levels of the melanogenic enzymes TRP-1, TRP-2, and microphtalmia-associated transcription factor (MITF) in B16F10 mouse melanoma cells." (PMID 33917985, 2021). "Moreover, in glycolytic melanomas, HIF1α suppresses transcription of the microphthalmia-associated transcription factor (MITF), which regulates peroxisome proliferator-activated receptor γ 1-α (PGC1α), resulting in OXPHOS inhibition." (PMID 33498757, 2021). "The melanocyte-inducing transcription factor (MITF) is also mutated in some sporadic melanomas." (PMID 34680938, 2021). "Similarly, we found that miR-100-5p and miR-125b-5p formed an independent network hub, mirroring the association of these microRNAs with ‘MITF-low’ melanomas from previous TCGA analyses." (PMID 34771465, 2021). "MITF is a major regulator of melanoma proliferation and progression, and mutations in MITF are associated with Tietz albinism-deafness syndrome, Waardenburg syndrome type 2A, and melanoma development." (PMID 33875769, 2021). "MITF protein was significantly reduced in PANX1-deficient melanoma cells." (PMID 33647315, 2021). "Despite these advances, loss of MITF found in melanomas with an invasive phenotype suggests loss of pigmentation, indicating a need to identify new molecular markers for detecting aggressive and invasive melanomas." (PMID 37849907, 2021). "Finally, MiTF-CX was found to be highly expressed in the cervix during pregnancy and MITF-Mdel, a splice variant of MITF-M, was identified in melanocytes and melanoma cell lines." (PMID 33441180, 2021). "We did not observe a correlation between MITF expression and the most common BRAF, NRAS, and NF1 mutations found in melanoma, indicating that the gene expression changes observed are controlled via transcriptional regulation, directly or indirectly imposed by MITF." (PMID 33438577, 2021). "While most PAX8+ and PAX2+ carcinomas are rarely confused with melanoma, cases of MiTf family altered renal cell carcinoma (MiTF-RCC) may pose a diagnostic challenge owing to the frequent patchy expression of melanocytic markers." (PMID 34449584, 2021). "SAMMSON (survival-associated mitochondrial melanoma-specific oncogenic non-coding RNA)—located downstream of the specific oncogene of melanoma microphthalmia-associated transcription factor (MITF)—is an oncogenic lncRNA expressed in more than 90% of human melanomas." (PMID 33503876, 2021). "Since suppression of MITF activity is linked to invasiveness and tumor-initiating capacity in melanoma, presumably invasive or circulating MITFLow cells would be more susceptible to NK-mediated cell death than proliferating or more differentiated MITFHigh cells." (PMID 33789714, 2021).
melanoma (continued). "To assess the effects of permanent loss of MITF in melanoma cells, we used the clustered regularly interspaced short palindromic repeats (CRISPR)-Cas9 technique to generate MITF knockout (KO) cell lines in the human hypo-tetraploid SkMel28 melanoma cell line (containing four copies of MITF)." (PMID 33438577, 2021). "As the increases in STAT3 phosphorylation and AXL expression associated with a decrease in MITF expression have been associated with the resistance of melanoma cells to targeted therapies, we asked whether RICTOR/mTORC2 could play a role in resistance." (PMID 34680615, 2021). "As MITF is central to the melanoma phenotype switching model, we were interested whether loss of MITF would be consistent with the published transcriptional signatures linked to phenotype switching in melanoma cells." (PMID 33438577, 2021). "Other studies identified treatment resistance mechanisms to targeted treatment against the mutated BRAF serine/threonine protein kinase including repression of the melanoma differentiation gene microphthalmia-associated transcription factor (MITF) and induction of AXL receptor tyrosine kinase." (PMID 33535416, 2021). "After MITF was revealed as a new candidate, we performed reporter, Western blot, and immunofluorescence assays to investigate the functional consequences of the identified variants, using melanoma (G361) and mouse embryonic fibroblast (NIH/3T3) cells." (PMID 32728090, 2020). "Regardless, we observed a high co-occurrence of MC1R variants and high MITF expression in melanoma patients (up to 38% co-occurrence), indicating that a subset of melanoma may be driven by mechanisms similar to those reported for the model presented here." (PMID 32605315, 2020). "Importantly, increased NAD+ levels render BRAFV600E melanoma cells resistant to vemurafenib and this was associated with epigenetic changes and reduced MITF expression." (PMID 33276788, 2020). "Therefore, the loss of A-SMase observed during melanoma progression accounts for the upregulation of MITF as well as for some of its downstream targets CDK2, Bcl-2 and c-MET." (PMID 32858889, 2020). "In addition to its utility as a diagnostic marker for melanoma, MITF has also been found to increase susceptibility to the co-occurrence of melanoma and renal cell carcinoma (RCC)." (PMID 32429485, 2020). "Since β‐catenin‐induced melanomas require functional MITF and loss of MITF expression affects the corresponding expression of c‐Myc, thus the role of MITF seems important in distinction of the immune evasion mechanisms in melanoma." (PMID 32147909, 2020). "In addition to melanoma, several tumors are associated with the dysregulation of the MITF gene, including renal cell carcinoma, clear cell sarcoma, prostate cancer, and chronic myeloid leukemia, but there are no reports of its involvement in OvCa." (PMID 33371469, 2020). "Indeed, the progression towards an invasive phenotype in melanoma has been linked to the downregulation of the microphthalmia-associated transcription factor (MITF) oncogene, which in turn leads to reduced lipogenesis." (PMID 32932943, 2020). "Interestingly, the PI3K-AKT pathway, which is commonly activated in many cancers, including melanoma, seems to be under MITF regulation in Hermes 4C with the MC1R inactive variant background." (PMID 32605315, 2020). "The COLO829 line represents an invasive type of melanoma that is still convertible (upon PLX4032 treatment) to a proliferative phenotype, whereas the A375 line is a relatively good model of the MITF expression-associated features of a proliferative type of melanoma." (PMID 33202765, 2020). "Of note, C2-ceramide was shown to reduce MITF expression in human melanocytes, suggesting that ceramide could affect the phenotype switching associated with melanoma progression." (PMID 33121001, 2020).
melanoma (continued). "Melanoma cells with BRAFV600E mutations are characterized by altered MITF expression and activity." (PMID 32605090, 2020). "In addition, high levels of CDR1as have been preferentially associated with melanoma cell state marked by low MITF level and high AXL level." (PMID 32340261, 2020). "Thus, the proliferative state of melanoma is associated with the robust and widespread binding of LTR5_Hs by MITF." (PMID 33202765, 2020). "In conclusion, MITF loss drives melanoma cell plasticity and phenotypic switching that correlates with reduced differentiation and immunogenicity, this loss also limits antitumor efficacy through the production of an inflammatory milieu that shapes an immunosuppressive TME." (PMID 33276788, 2020). "In addition, treatment with GS was shown to inhibit melanogenesis in B16 murine melanoma cells through the reduction of tyrosinase, microphthalmia-associated transcription factor (MITF), and tyrosinase-related protein (TRP-1 and TRP-2)." (PMID 36046484, 2020). "However, Potrony and colleagues reported that during 10 years of dermatological surveillance of patients at high risk of melanoma, the only two fast-growing melanomas (growth rate greater than 0.4 mm per month) were diagnosed in MITF+ patients." (PMID 32054529, 2020). "Thus, our KD Rec A375 model recapitulates MITF-associated aspects of phenotype switching in melanoma patients to some degree." (PMID 33202765, 2020). "Given the fact that melanomas, under harsh conditions, can become enriched in MITFlow cells and that these are more capable of escaping T-cell recognition, loss of MITF may be a mechanism for tumor cells to evade the immune system." (PMID 32245160, 2020). "We hypothesized that, in addition to its role in melanoma, MITF is associated with the progression of OvCa." (PMID 33371469, 2020). "Significantly, GSVA analysis of the CCLE melanoma cell lines revealed that although there are some exceptions, in general a high constitutive hypoxia gene expression signature is associated with low levels of MITF mRNA." (PMID 31207090, 2019). "In addition, forced expression of GTF2H1 was associated with an increase in proliferation of IHM and melanoma cells exhibiting a complete lack or low abundance of MITF, respectively." (PMID 30651597, 2019). "The miR-340 is also described to regulate the master regulator of melanocyte development and melanoma progression, microphthalmia-associated transcription factor (MITF), and MAPK-signalling by modulating the expression of multiple components of this pathway in vitro." (PMID 31687076, 2019). "The MITF/PGC1a axis has also been implicated in the melanoma cell response to targeted therapy." (PMID 31461993, 2019). "The presence of low levels of β-Catenin, associated with low MITF levels in V600BRAF melanoma cell lines, could be linked to autophagy activation in these cell lines, as proved by the high TFEB levels revealed in this study." (PMID 30634982, 2019). "PGC1A and MITF are a notorious pair implicated in overcoming melanoma’s glycolytic dependence and in development of rapid resistance to BRAF-inhibitor therapy, a cornerstone in recent melanoma therapeutics, and are currently in clinical trials as an adjuvant in melanoma immunotherapy." (PMID 31547367, 2019). "The microphthalmia-associated transcription factor (MITF) is involved in the development of melanocytes and melanoma and to regulate transcription of a broad range of genes, ranging from genes important for pigment production to genes involved in cell cycle regulation, migration and survival." (PMID 31231417, 2019).
melanoma (continued). "Furthermore, it has been shown that MITF expression is lost in BRAFV600E mutated melanoma, and that a low expression of MITF leads to increased metastatic ability of melanoma cells." (PMID 31416288, 2019). "Interestingly, MITF represents the major regulator of the pigmentation pathway, and at the same time amplification of the MITF locus was shown to be associated with melanoma metastasis." (PMID 30823658, 2019). "On the other hand, we checked the impact of ERK activation on MITF (melanogenesis associated transcription factor) because MITF is a critical transcription factor for melanocyte and melanoma cell proliferation, whose stability is reduced when phosphorylated by MAPK or KIT." (PMID 31040916, 2019). "Furthermore, we also found different MITF levels in melanoma cell lines harboring BRAF mutations, as compared to wtBRAF." (PMID 30634982, 2019). "Acquisition of a low microphthalmia-associated factor MITF state together with activation of epithelial-mesenchymal transition (EMT) can transform melanoma cells to a highly invasive, dedifferentiated and therapy-resistant phenotype with cancer cell plasticity." (PMID 30900145, 2019). "It has been reported that MITF expression is elevated or mutated in melanoma." (PMID 30084054, 2019). "Furthermore, in a retrospective study, it was demonstrated that low MITF expression is associated with a worse prognosis in melanoma patients." (PMID 31514305, 2019). "Melanocyte‐specific isoform of MITF (microphthalmia‐associated transcription factor) is a pivotal protein determining the melanocyte lineage identity and conferring a strong antiapoptotic activity to melanoma cells." (PMID 29369499, 2018). "In melanoma, the balance of master regulator microphthalmia-associated transcription factor (MITF) and tyrosine kinase AXL has been shown to function as rheostat determining the transition between proliferative and invasive state—with highest MITF levels promoting neuronal differentiation." (PMID 29794999, 2018). "The different effect of AgGom and HiGom could be explained due to amplification of microphthalmia-associated transcription factor (MITF) expression in the different melanoma lines, which has been linked to MAPK inhibition." (PMID 30068931, 2018). "The EMT features and increased invasiveness are associated with lower levels of the pivotal lineage identity maintaining and melanoma‐specific transcription factor MITF (microphthalmia‐associated transcription factor), whereas increased proliferation is linked to higher MITF levels." (PMID 29369499, 2018). "Microphtalmia-associated transcription factor (MITF), a transcription factor whose expression is largely restricted to the melanocytic lineage, has been shown to be amplified in 30% melanomas and required for survival of a subset of melanomas." (PMID 29629336, 2018). "Advanced melanomas are frequently pigmented indicating that differentiation does not impede metastatic growth, most probably because in melanoma the differentiated phenotype is closely linked to proliferation through MITF." (PMID 29545604, 2018). "Moreover, the amplification of microphthalmia-associated transcription factor (MITF) gene seems to play a role in melanoma progression, while the role of the genomic amplification for EGFR and cMET genes is less clear." (PMID 29492214, 2018). "Moreover, lebein reduces proliferation and increases the differentiation of melanoma cells by upregulating microphthalmia-associated transcription factor (MITF) through inhibition of extracellular signal-regulated kinase (ERK) phosphorylation." (PMID 30360399, 2018). "MC1R and MITF are considered moderate-risk genes for melanoma susceptibility." (PMID 27776349, 2017).